RN7SL361P (RNA, 7SL, cytoplasmic 361, pseudogene)
Gene: Miscellaneous RNA gene on chromosome 2 (60,640,705 to 60,641,002, forward strand). Ensembl gene ENSG00000242158.
Homologues: Orthologues: chimpanzee Metazoa_SRP (98% identical), macaque Metazoa_SRP (95% identical). Paralogues in human: RN7SL1 (83% identical), RN7SL2 (83% identical), RN7SL3 (82% identical), RN7SL126P (80% identical), RN7SL597P (80% identical), RN7SL357P (80% identical), RN7SL507P (79% identical), RN7SL665P (79% identical), RN7SL709P (79% identical), RN7SL118P (79% identical), RN7SL296P (79% identical), RN7SL479P (79% identical), and 702 more.